S100A11 (S100 calcium binding protein A11)
Diseases named in the same sentence as S100A11 in open-access papers (continued):
Sharing a sentence is not in itself a finding about the gene and the disease.
cancer (continued). "To clarify how intracellular S100A11 aids cancer cell activation, we tried to identify S100A11 binding proteins, resulting in novel binding partners in the inner membrane, many of which are desmosome proteins." (PMID 38842658, 2024). "Our efforts revealed that overexpression of S100A11 promotes proliferation and migration, and downregulation inversely dampens those cancer behaviors." (PMID 38842658, 2024). "Among these elevated proteins, S100A11 alone was significantly correlated with a cancer-relevant lower survival when it was expressed at consistently high levels under various conditions." (PMID 38595825, 2024). "Our study also revealed the novel downstream mediator S100A11, and its downregulation resulted in reduced cancer stemness properties." (PMID 38169544, 2024). "S100A11 has been reported to be upregulated in various cancers, including pancreatic and colorectal." (PMID 38842658, 2024). "Cancer cells, instead, use S100A11 for their growth advantage through the secretion of S100A11 into the outside fluid, which stimulates receptors for advanced glycation end product (RAGE) on cancer cells in an autocrine manner." (PMID 38842658, 2024). "We previously demonstrated that S100A11 is actively secreted from several types of cancer cells, and the secreted S100A11 acts to fuel cancer progression." (PMID 38595825, 2024). "Among these genes, a particular type, S100A11, has been identified as an accelerator of cancer cell migratory outgrowth, which we have revealed." (PMID 39570532, 2024). "The product of S100A11 gene is a calcium-binding protein that enhances epithelial-to-mesenchymal transition in cancer." (PMID 37373166, 2023). "We will conduct a series of functional and animal experiments to further verify the role of S100A11 in pan-cancer." (PMID 36605485, 2023). "In intrahepatic cholangiocarcinoma, S100A11 had the potential to promote cancer cell proliferation by regulating the P38/MAPK signaling pathway." (PMID 38129538, 2023). "Recent studies have found that S100A11 is associated with high-grade HCC and poor prognosis through its promotion of cancer cell proliferation and migration." (PMID 37166978, 2023). "In this study, we analyzed the differential expression, genetic alteration, and potential prognostic value of S100A11 in pan-cancer." (PMID 36605485, 2023). "The Genomics of Drug Sensitivity in Cancer database was used to investigate the effect of S100A11 on the efficiency of anticancer drugs." (PMID 36605485, 2023). "We used UniCox to analyze the correlation between S100A11 and the prognosis of patients with cancer." (PMID 36605485, 2023). "S100A11 is aberrantly expressed in many carcinomas and serves a crucial function in cancer development." (PMID 38129538, 2023). "Several studies have shown that S100A11 is aberrantly expressed at both the mRNA and protein levels in a variety of malignant tumors." (PMID 38129538, 2023). "We discovered that the expression level of S100A11 in pan-cancer was obviously correlated with most immunosuppressive cells, such as TAMs and TAFs." (PMID 36605485, 2023). "Proinflammatory cytokines S100A8/S100A9/S100A11 are calcium‐binding proteins that are upregulated in human cancer." (PMID 36967480, 2023). "This study used public data from The Cancer Genome Atlas (TCGA) and the Genotype-Tissue Expression (GTEx) database to evaluate the expression of S100A11." (PMID 36605485, 2023). "We further analyzed immune cell infiltration using TIMER2 and ImmuCellAI databases, and found that the expression of S100A11 was significantly related to most immunosuppressive cells (TAMs, TAFs, and Tregs) in pan-cancer." (PMID 36605485, 2023). "Spearman correlation of the 16 hypoxia genes and 151 chemo drugs in the Genomics of Drug Sensitivity in Cancer database revealed that the expression of DCBLD2, PLEC, S100A11, PLAT, PPAP2B and LAMC2 was associated with resistance to most chemotherapies." (PMID 35155430, 2022).
cancer (continued). "S100A11 has been shown to regulate multiple biological functions related to the progression and metastasis of various cancer types." (PMID 35752610, 2022). "Although accumulating evidence has confirmed that TKT promotes the proliferation and migration of various cancer cells, the specific biological mechanisms underlying the regulation of TKT mediated by S100A11 remain incompletely understood." (PMID 35752610, 2022). "Identified Protein S100A11 was previously found to be upregulated in human cancer tissues promoting growth, invasion, and migrations of cancer cells." (PMID 36536419, 2022). "Recently, studies have found that, the expression of S100A11 is positively correlated with the degree of cancer progression and an unfavourable clinical prognosis." (PMID 35752610, 2022). "Increased S100A11 expression has been observed in lung cancer, which activates Wnt/β-catenin pathways to facilitate the development of drug resistance and cancer metastasis." (PMID 34712325, 2021). "DNA hypomethylation also contributes to the regulation of the expression of S100A6, S100A8 and S100A11 in various cancers." (PMID 33466593, 2021). "S100A11 and MMP-9 were both highly expressed in the serum of patients with EOC and were associated with cancer development, invasion, and metastasis." (PMID 33763485, 2021). "S100A11 is highly expressed in various cancers and related to poor differentiation, distant metastasis, and shorter disease-free survival." (PMID 31703598, 2019). "Furthermore, mRNA levels of annexin A1 and S100-A11 positively correlated in 1,072 comprehensively characterized human cancer cell lines from the Cancer Cell Line Encyclopedia data set, confirming that this association is also relevant for cancer types other than colorectal." (PMID 31545917, 2019). "Accumulating evidence indicates that S100A11 expression is upregulated in various cancers and promote cancer development." (PMID 29362358, 2018). "To gain insight into the intracellular signaling events induced by the neutralization of extracellular S100A11, we investigated the key molecules regarding to cancer progression." (PMID 29362358, 2018). "S100A11, a Ca2+-binding small protein with two EF-hands, is frequently upregulated in various human cancers." (PMID 29362358, 2018). "Of the differentially expressed proteins, CLU, NDRG1, CD166, S100A11 and Galectin-1 were carcinoma-related proteins affected by rGal3C." (PMID 28701735, 2017). "To observe the effect of endogenous S100A11 localized to cytoplasm and nucleus on the potential of homing capacity, we injected cancer cells into nude mice through tail vein to observe lung nodules formation." (PMID 27181092, 2016). "Despite the significant role of S100A11 in cancer progression, the downstream mechanism and molecular targets of S100A11 remains to be elucidated." (PMID 27181092, 2016). "In the current analysis, a significant correlation was found between S100A11 overexpression and worse clinical prognosis, and it was therefore possible that overexpression of S100A11 in the cancer cells resulted in more aggressive disease." (PMID 27181092, 2016). "For example, both ANO1 and S100A11 have been reported to have important roles in tumorigenesis and cancer metastasis." (PMID 26902283, 2016). "As a member of the S100 protein family, S100A11 expression is often upregulated in human cancer tissues." (PMID 25780452, 2015). "Numerous studies have demonstrated that S100A11 plays an important role in the progression of cancer." (PMID 25780452, 2015). "For example, over-expression of S100A2, S100A3, S100A6, S100A8/A9, and S100A11 is related to several types of cancer, whereas other types of cancer are characterized by the under-expression of these same proteins." (PMID 25988147, 2014). "Moreover, further research is needed to explore the broader implications of S100A11-mediated suppression of senescence in cancer progression and resistance to therapies." (PMID 40374593, 2025).
cancer (continued). "Cancer cells are better at using S100A11 for other migration." (PMID 38842658, 2024). "Therefore, screening was performed using multiple cancer cell lines to investigate further which cancer cells’ expression of S100A11 is elevated in agreement with the result of cancer tissue analysis." (PMID 38842658, 2024). "Although the increased expression of S100A11 may benefit clinical usage, the question of how increased expression of S100A11 is induced in cancer cells remains elusive." (PMID 38842658, 2024). "Next, we asked whether the plasmin production mediated by annexin A2/S100A11 complex on the cell surface of the LOXL4-positive TNBC cells promotes cancer metastasis." (PMID 38595825, 2024). "Our findings revealed the importance of S100A11 in pan-cancer and suggested that S100A11 might have the potential to regulate the immunosuppressive TME." (PMID 36605485, 2023). "Additionally, the upregulation of S100A11 expression made patients with cancer resistant to the treatment of most anticancer drugs, such as sorafenib." (PMID 36605485, 2023). "Targeting S100A11 might activate the immune microenvironment and improve the survival of patients with cancer." (PMID 36605485, 2023). "We performed GSVA in pan-cancer to analyze the potential pathways with the involvement of S100A11." (PMID 36605485, 2023). "Moreover, the resistance of cancer cells to chemotherapeutic agents such as fluorouracil (5-FU) and cisplatin was reduced upon S100A11 knockdown." (PMID 38129538, 2023). "S100A11 is abnormally expressed in a large number of malignancies and could engage in the development and progression of cancers." (PMID 38129538, 2023). "The upregulation of S100A11 expression made patients with cancer resistant to sorafenib treatment." (PMID 36605485, 2023). "Importantly, S100A11 released by cancer cells is known to stimulate a change in fibroblast phenotype upon binding to the RAGE receptor." (PMID 36475545, 2022). "ELDA clarified the effect of S100A11 on cancer stem cell (CSC) frequency in vivo." (PMID 35752610, 2022). "To date, S100A11 was shown to be highly secreted by cancer cells and HCC." (PMID 36232334, 2022). "In contrast, S100A11 expression is downregulated as cancer progresses to a worse phenotype." (PMID 34527585, 2021). "Furthermore, in a recent study on human cancers, S100A11 was found to be highly enriched in the proteomic profile of extracellular vesicles and particles (EVPs) in human pancreatic adenocarcinoma." (PMID 34179021, 2021). "We detected increased levels of S100A11 in cancer cells with various secretion levels." (PMID 29362358, 2018). "As cPLA2 was upregulated in 64% of NSCLC samples overexpressing S100A11, compared to normal tissues, targeting TSN or S100A11 may be particularly beneficial for anti-cancer treatment in these cases." (PMID 25940438, 2015). "A recent study showed that S100A11 is required for the survival of invasive cancer cells." (PMID 25780452, 2015). "In contrast, S100A11 has been shown to be overexpressed in many human cancers." (PMID 23166536, 2012). "Moreover, they found a translocation of S100A11 expression from exclusively nuclear location in normal tissues to cytoplasmic and nuclear in all common cancers." (PMID 16265347, 2005). "S100A11, a member of the S100 family, may mediate signal transduction in response to internal or external stimuli and it plays various roles in different diseases such as cancers, metabolic disease, neurological diseases, and vascular calcification." (PMID 34179021, 2021). "In addition, S100A11 may have an effect on the proliferation of cancer cells through nucleocytoplasmic translocation." (PMID 33299138, 2020).
cancer (continued). "Conversely, knockdown of S100A11 in HCC cells increased the expression of anti-cancer M1 macrophage markers CD80 and CD86 but suppressed the expression of pro-cancer M2 markers CD204 and CD206 upon co-culture with THP-1 derived macrophages." (PMID 38169544, 2024). "For the extracellularly releasing process, S100A11 is required to meet PEX14, a peroxisome membrane protein, leading to peroxisomal co-option, subsequent homodimerization, and secretion in cancer cells." (PMID 38842658, 2024). "The elevated expression of S100A11 predicted worse OS, DSS, DFI, and PFI in patients with cancer, especially in LGG, KIRC, PAAD, and LIHC." (PMID 36605485, 2023). "In order to indicated the role of the family members in HCC development, we further analyzed the expression of S100A4, S100A6, S100A10, S100A11 and S100A16 in pan-cancer, and the results suggested that they were highly expressed in most tumors." (PMID 37420211, 2023). "In the cancer cell lines, statistically significant correlations were found between S100P and S100A8 (R = 0.91), and S100A11 (R = 0.73)." (PMID 37627239, 2023). "In basal‐like cancer, there was a positive correlation of KLK6 and S100A11 and S100A2, in accordance with our findings." (PMID 30980596, 2019). "Therefore, S100A11 might act sometimes as an oncogene, and sometimes as a suppressor gene, and have a key role in the progression of malignant tumors based on the balance of its ambivalent effect, which may be different depending on cancer types." (PMID 29362358, 2018). "For example, the over-expression of S100A2, S100A3, S100A6, S100A8/A9, S100A11 and S100A14 have been documented in several cancer types." (PMID 30018736, 2018). "Second, S100A11 and ANXA1 proteins have recently been shown to protect against cell membrane damage and promote survival of cancer cells." (PMID 29844306, 2018). "Gene expression analysis performed using A549 NSCLC cells after silencing of TSN revealed several novel candidates for anti-cancer therapy downstream from TSN, such as S100A11, ATP6V1F, MDC1, BNIP3, etc., which are implemented in the cell death mechanism." (PMID 25940438, 2015). "For example, S100A4, S100A6, S100A7 and S100B play oncogenic roles in cancer development, whereasS100B, S100A2, and S100A11 are believed as TSGs." (PMID 23894350, 2013). "On the other hand, most of S100A11 is still present within cancer cells; however, the intracellular role of S100A11 in cancer cells has not been fully elucidated." (PMID 38842658, 2024). "Besides, our study also observed that S100A11 was significantly related to MHC genes, immunosuppressive genes, chemotactic factors, and chemokine receptors in pan-cancer." (PMID 36605485, 2023). "Three proteins (CPE, S100A11, and PCOLCE) are reported tumorigenic in OS and/or other cancer." (PMID 36943734, 2023). "The higher levels of S100A2, S100A11, and S100A14 transcript in the eight cancer cell lines than in the HPNE control cell line suggest that these three S100s might modulate the behavior of the cancer cells." (PMID 37627239, 2023). "Therefore, we first analyzed the expression patterns of these proteins in the TCGA‐BLCA and Xiangya BLCA cohorts and found that S100A5, S100A7, S100A11, S100A14‐16, and S100B were significantly higher in carcinoma tissues than normal tissues in both cohorts." (PMID 37414584, 2023). "However, most of S100A11 is still present within cancer cells, although the intracellular role of S100A11 in cancer cells has not been fully elucidated." (PMID 38842658, 2024). "The finding that S100A11 decreased the activity of the PPP, of which TKT is a key enzyme, prompted us to investigate whether S100A11 regulates the expression of TKT for the survival and biosynthesis of cancer cells." (PMID 35752610, 2022). "In addition, we have also identified the protein S100-A11, which is a protein often upregulated in different types of human cancer, and its potential as a therapeutic target has not been evaluated yet in patients with MM." (PMID 33833982, 2021).
cancer (continued). "Although many studies have indicated that the regulation of cancer-associated fibroblasts (CAFs) through known targeted pathways may be a good choice to treat PDAC, the mechanism of S100A11 in fibroblasts is not yet clear." (PMID 34527585, 2021). "In our study, gene expression analyses show that S100A2, S100A11, and S100P expression levels in CRC tissues are significantly higher than those in noncancerous tissues, and S100A3 and S100A9 mRNAs are highly expressed in cancer tissues compared with normal tissue controls." (PMID 33294444, 2020). "Among these candidate genes, S100A11 (r = −0.38, P = 6.23 × 10−14), has the highest negative correlation with PCK1 in The Cancer Genome Atlas (TCGA) database and has been reported to act as an oncogene in several tumors." (PMID 37166978, 2023).
infection (10 papers, 2010 to 2025). The state of being infected such as from the introduction of a foreign agent such as serum, vaccine, antigenic substance or organism. "Utilizing S100a11-deficient mice, it was established that in vivo S100a11 promotes CCL2-mediated monocyte recruitment to the site of infection and significantly contributes to host survival." (PMID 40854593, 2025). "It has been recently reported that after infection by Toxoplasma gondii, human monocytes detect S100A11 protein, which has been released from infected cells in a caspase-1-dependent manner." (PMID 34179021, 2021). "The infection efficiency of Ad-S100A11 in brain tissue was confirmed by western blotting and immunofluorescence staining." (PMID 29844306, 2018). "A few mRNAs of immunological interest, namely Lyz1, S100a11, and Cxcl3 exhibited elevated ribosome occupancy in all infection conditions." (PMID 28383283, 2017). "Furthermore, during acute infection, the alarmin s100a11 promotes a Ccl2-mediated monocyte recruitment to the site of infection." (PMID 39446964, 2024). "Therefore S100A11 plays a role of innate immune sensor in this infection." (PMID 34179021, 2021). "In addition, the type 1 IFN related genes (OAS1G, OAS2, OASL1, OASL2, S100A6, S100A8, S100A9, S100A11) that are necessary for activation of the inflammasome in Francisella novida-infected macrophages, were highly induced over the course of infection and peaked at 24 hpi." (PMID 21110886, 2010). "The expression level of several proinflammatory genes including TYROBP, S100A8, S100A11, LBP and CD88 were increased significantly after infection." (PMID 39398025, 2024). "The differences between infection in S100A10 KO versus A2t KO cells could be explained by the fact that S100 family members S100A4, S100A6, and S100A11 are also able to complex with AnxA2 and are expressed in cervical epithelium." (PMID 30076379, 2018).
metabolic disease (4 papers, 2021 to 2025). A congenital disorder (due to inherited enzyme abnormality) or acquired (due to failure of a metabolically important organ) disorder resulting from an abnormal metabolic process. "S100A11 plays a role in tumors, metabolic diseases, neurological diseases, and vascular calcification." (PMID 36872321, 2023). "Although there are relatively few studies on S100A11 in metabolic diseases, these published works indicate that S100A11 may play an important role in the development and progression of other metabolic diseases, not only T2D and NAFLD." (PMID 34179021, 2021).
neurological diseases (2 papers, 2021 to 2025). "In another severe neurological disease, autoimmune encephalitis, S100A11 was also found to be up-regulated and hypomethylated." (PMID 34179021, 2021). "According to these studies, like its role in tumors, S100A11 can also have a dual role in neurological diseases." (PMID 34179021, 2021). "S100A11 has also been shown to be an important factor in neurological diseases." (PMID 34179021, 2021).